SPMIP8 (sperm microtubule inner protein 8)
Description:
Microtubule inner protein (MIP) part of the dynein-decorated doublet microtubules (DMTs) in flagellum axoneme. May serve to reinforce and thus stabilize the microtubule structure in the sperm flagella.
Synonyms: TEPP
Tractability: No criterion of Open Targets' tractability assessment is met for any kind of drug.
Gene: Protein-coding gene on chromosome 16 (57,976,435 to 57,988,116, forward strand). Ensembl gene ENSG00000159648.
Subcellular location: Cytoplasm, cytoskeleton, flagellum axoneme
Gene Ontology:
Molecular function: protein binding
Biological process: flagellated sperm motility
Cellular component: axonemal A tubule inner sheath; sperm flagellum
Genetic constraint (gnomAD): Loss-of-function variants: 24 observed, 28.44 expected, observed/expected ratio (o/e) 0.84, 90% interval 0.61 to 1.19. The upper end of that interval is the gene's LOEUF score, 1.19, which puts it in group 5 of 6, group 1 being the genes least tolerant of losing a copy. Missense variants: 296 observed, 282.23 expected, observed/expected ratio (o/e) 1.05, 90% interval 0.95 to 1.15. Synonymous variants: 115 observed, 111.59 expected, observed/expected ratio (o/e) 1.03, 90% interval 0.88 to 1.2.
Homologues: Orthologues: macaque SPMIP8 (97% identical), chimpanzee SPMIP8 (94% identical), guinea pig SPMIP8 (88% identical), dog SPMIP8 (85% identical), pig SPMIP8 (84% identical), mouse Spmip8 (79% identical), rabbit SPMIP8 (70% identical), rat Spmip8 (56% identical), tropical clawed frog spmip8 (40% identical).
Diseases named in the same sentence as SPMIP8 in open-access papers:
SPMIP8 is named in the same sentence as 17 diseases in open-access papers, as found by Europe PMC text mining. Sharing a sentence is not in itself a finding about the gene and the disease.
SPMIP8 shares sentences with these, for which no sentence is quoted: infection (6 papers); tumor (5); cancer (1); cardiomyopathy (1); Chlamydia infection (1); co-infection (1); encephalomyelitis (1); Endotoxemia (1); glioma (1); liver cancer (1); microcephaly (1); ovarian carcinoma (1); pancreatic cancer (1); periodontitis (1); renal fibrosis (1); Sepsis (1); ZIKV infection (1).